RET (ret proto-oncogene)
Diseases named in the same sentence as RET in open-access papers (continued):
Sharing a sentence is not in itself a finding about the gene and the disease.
pheochromocytoma (continued). "The ENDOGENE Panel v1.0 identified the RET p.M918T (rs74799832) mutation in a 33-year-old male patient in whom the referring clinical diagnosis was a unilateral pheochromocytoma." (PMID 34439371, 2021). "According to the NCBI ClinVar database, variant rs1799939 in the RET gene is associated with multiple endocrine neoplasia, hereditary cancer-predisposing syndrome, renal dysplasia, and pheochromocytoma." (PMID 32708070, 2020). "This is the first case to show the activation of unfolded protein response in the pheochromocytoma with the novel somatic mutation in RET gene." (PMID 32571297, 2020). "We report a novel RET germline mutation (exon 15; c.2692G>T (D898Y)) in a pheochromocytoma patient, as well as in her two asymptomatic sons and older sister." (PMID 29850289, 2018). "RET, which encodes another tyrosine kinase, can be expressed as an intron 2-retaining variant that is detectable in 19% of pheochromocytomas." (PMID 29535836, 2018). "When the patient has adrenal medullary disease, known as pheochromocytoma, the presence of associated adrenal medullary hyperplasia indicates that RET pathogenesis is most likely, since this phenomenon is typically found in patients with MEN2." (PMID 30217041, 2018). "The transcription profile of TMEM127-mutant pheochromocytomas was found to be similar to that of tumors with mutations in the RET and NF1 genes." (PMID 28187001, 2017). "MTC is usually the first endocrinopathy to appear in MEN2, with frequency and age of development of hyperparathyroidism or phaeochromocytoma dependent on the RET mutation inherited." (PMID 28965289, 2017). "Multiple endocrine neoplasia-2 is one of the earliest syndromes to have been associated with phaeochromocytoma and is caused by an activating (gain-of-function) germline mutation in the RET proto-oncogene located on chromosome 10q11.2." (PMID 29166454, 2017). "Somatic mutations in RET have been detected in approximately 5% of sporadic pheochromocytomas and paragangliomas." (PMID 28187001, 2017). "To better characterize the function of PNMT in PCC/PGL, we analyzed a large (125 samples) public PCC/PGL microarray expression profile dataset (GSE19987) with a variety of mutations in pheochromocytoma susceptibility genes such as RET, VHL, SDHB and SDHD." (PMID 27007161, 2016). "The COMETE cohort has demonstrated the occurrence of somatic mutations in VHL and RET genes in 14% of sporadic pheochromocytoma/paraganglioma, one germ-line, and three somatic mutations in the MAX were described by the same cohort." (PMID 26347711, 2015). "Our report suggests that cases with S891A mutation, akin to those with other RET mutations, require screening for pheochromocytoma." (PMID 24449023, 2014). "Further studies should be performed on a larger group of pheochromocytoma patients with a VHL or RET gene mutation to confirm these observations." (PMID 24523932, 2014). "The coexistence of pheochromocytoma with interscapular pruritic lesions strongly suggests a mutation in codon 634 of the RET gene." (PMID 24899893, 2014). "It was believed that the risk of developing a phaeochromocytoma in carriers of a mutation in exon 8 of the RET gene was low." (PMID 24616773, 2013). "We present the case of a 30-year-old female who was diagnosed with hereditary phaeochromocytoma secondary to a rare gene mutation in exon 8 of the RET oncogene." (PMID 24616773, 2013). "In patients with familial pheochromocytoma screening for gene mutations in the RET, VHL, SDHB and SDHD gene is recommended since different familial syndromes can be revealed." (PMID 17922902, 2007). "Somatic VHL gene alterations are implicated in the pathogenesis of MEN2-associated pheochromocytomas, possibly through accumulation of RET protein." (PMID 16707008, 2006). "In the Geisinger MyCode cohort, 2 of the 77 RET variant carriers had potential pheochromocytoma." (PMID 40577012, 2025). "The RET proto-oncogene is a common pathogenic gene in pheochromocytoma." (PMID 37335636, 2023).
pheochromocytoma (continued). "Interestingly, somatic mutations in RET have been found in 23–70% of sporadic MTCs and 10–15% of sporadic pheochromocytoma patients, as well." (PMID 34777782, 2021). "Finally, the cortical admixture cluster is characterized by pheochromocytomas with NF1 somatic mutations as well as MEN2-related tumors with RET germline mutations." (PMID 33768452, 2021). "This is the first description of a RET D898Y mutation in a pheochromocytoma patient and her family." (PMID 29850289, 2018). "Considering the important role of RET in pheochromocytoma development, researchers further suggested that mutations in GDNF affecting its interaction with RET may be also associated with the disease." (PMID 28187001, 2017). "Furthermore, uncontrolled activation of the RAS/RAF/ERK pathway is observed in paragangliomas/pheochromocytomas with mutations in the RET and NF1 genes." (PMID 28187001, 2017). "Interestingly, a recent case report paper identify bilateral pheochromocytoma as the first manifestation of MEN2A disease in a patient of a family carrying the RET-S891A mutation." (PMID 25887804, 2015). "As the relationship between exon 8 mutations of the RET gene and familial phaeochromocytoma has only recently been discovered, it highlights the importance of extended genetic analysis in cases of apparently sporadic phaeochromocytoma in young patients or those with a strong family history." (PMID 24616773, 2013). "By the comparison of hypoxia- and Ras-associated pheochromocytoma, we have found that enhanced insulin like growth factor 1 signaling may be responsible for the activation of Src homology 2 domain containing transforming protein 1, the main co-factor of RET." (PMID 23106811, 2012). "Another study on the RET K666N mutation in a patient with MTC and bilateral pheochromocytoma (PHEO), who was homozygous for RET K666N, described important aspects of this mutation’s influence on the development of MTC and PHEOs in patients with MEN2 syndrome." (PMID 40476723, 2025). "In the UK, this is the testing strategy for individuals with phaeochromocytoma (<60 years), bilateral phaeochromocytoma or hyperparathyroidism (<50 years), which includes RET in the multigene NGS panel." (PMID 40138217, 2025). "Although 3′ kinase fusions predominate, 5′ kinase events, such as FGFR2/3 and RET 5′ fusions, also occur, e.g., in pheochromocytoma." (PMID 41465145, 2025). "These new genetic markers, along with the susceptibility genes like RET, NF1, VHL, SDH, and fumarate hydratase, are expanding our understanding of the genetic basis of pheochromocytoma." (PMID 40649858, 2025). "Inherited RET mutations give rise to MEN2, a condition in which benign and malignant endocrine neoplasms co-exist, such as MTC combined with pheochromocytoma or hyperparathyroidism." (PMID 40731793, 2025). "The patient carried the RET variant c.2410G>A, p.Val804Met is a well-known activating mutation involved in MEN2A with a moderate risk of MTC and an incidence of pheochromocytoma and primary hyperparathyroidism of less than 10%." (PMID 39398337, 2024). "In 2002, a study of germline (MEN2-related) and sporadic pheochromocytomas described the presence of the same 3 RET splice variants identified in the MTC cell line in pheochromocytomas (RET 2/4, RET 2/5 and RET 2/6)." (PMID 38566816, 2024). "Pheochromocytomas carrying TMEM127 mutations exhibit elevated levels of LAMTOR proteins, while generally, a loss of TMEM127 drives RET-mediated tumor transformation, deregulating membrane dynamics." (PMID 39336996, 2024). "The second cluster is defined by a kinase signature, including genes like RET (rearranged during transfection), NF1 (neurofibromin 1), and TMEM127 (a gene that encodes a membrane protein, mutations that are associated with pheochromocytomas." (PMID 39591360, 2024).
pheochromocytoma (continued). "The most prevalent activating mutation was RET M918T (n = 7), which apart from MTC was also reported across a spectrum of additional neuroendocrine tumors, including paraganglioma, pheochromocytoma, and carcinoid tumors." (PMID 37627175, 2023). "The concurrence of pheochromocytoma and MTC among the familial AMH cases supports a genetic association between familial pheochromocytoma and MTC with RET, SDHD, MAX, and NF1 pathological variants being reported." (PMID 36896586, 2023). "The RET variant V292M has already been reported in a 44-year-old man with unilateral MTC and unilateral pheochromocytoma, suggesting MEN2 syndrome." (PMID 37835559, 2023). "The syndromes associated with pheochromocytomas are multiple endocrine neoplasia 2 (MEN 2A and MEN 2B) linked to RET gene mutations, von Hippel–Lindau syndrome due to VHL gene mutations and neurofibromatosis type 1 associated with NF1 gene mutations." (PMID 37628857, 2023). "Cluster 2 PPGLs are built-up mostly by pheochromocytomas driven by variants in genes regulating kinase-driven pathways, including NF1, KIF1B, MAX, RET, TMEM127 and H-RAS." (PMID 35205664, 2022). "The ‘ion channel activity’ of the M4-M5 metaprograms is highly enriched among the RET tumor cells indicating a high secretory activity of the adrenal RET-pheochromocytoma tumor cells." (PMID 36046044, 2022). "A study from Turkey reported 18 RET C634G mutations in 88 individuals, while another study reported VHL mutations in two pheochromocytoma patients." (PMID 33777662, 2021). "Targeted sequencing detected germline RET variants in 697 individuals, including 245 MEN2, 120 sporadic medullary thyroid cancer (MTC), and 15 pheochromocytoma (PHEO) patients and their 493 relatives." (PMID 33827484, 2021). "Pheochromocytoma is rarely the first tumor to be diagnosed in RET carriers, as it usually presents in the third or fourth decade of life." (PMID 33938650, 2021). "RNA expression levels of RET were increased 139 times in her pheochromocytoma compared with her normal adrenal gland." (PMID 32571297, 2020). "Mutations in VHL, RET, NF1, SDHB, and SDHD account for 90% of all pheochromocytomas and paragangliomas." (PMID 32266384, 2020). "Variant rs1800862 (RET), according to NCBI ClinVar, is associated with multiple endocrine neoplasia, pheochromocytoma, and Hirschsprung disease, and is dominant." (PMID 32708070, 2020). "RET mRNA expressions in the patient’s pheochromocytoma were increased 139 times more than in her normal adrenal gland." (PMID 32571297, 2020). "Gene expression microarray profiling showed that these tumors clustered with NF1-, RET,- and HRAS-mutated pheochromocytomas, indicating activation of the MAPK and PI3K-AKT signal transduction pathways." (PMID 29159601, 2018). "Known pathogenic variation in SDHB/RET, BRCA1/2, and MMR genes is thought to be responsible for a subset of pheochromocytoma and paraganglioma, breast, ovarian, colon, and uterine cancers in TCGA." (PMID 30217226, 2018). "VHL, RET, NF1, SDHB, and SDHD are major susceptibility genes, accounting for 90% of familial pheochromocytomas/paragangliomas, whereas TMEM127, SDHA, SDHC, SDHAF2, and MAX are minor susceptibility genes responsible for 10% of these tumors." (PMID 30456751, 2018). "Both germline and somatic mutations in KIF1B gene have been found in pheochromocytoma, occasionally occurring in combinations with mutations in other genes, such as NF1, RET, VHL, and SDHx." (PMID 29504908, 2018). "Conversely, both germline and somatic mutations in this gene have been found in pheochromocytomas, occasionally occurring in combinations with mutations in other genes, such as NF1 or RET as well as VHL or SDHx." (PMID 28187001, 2017). "mTOR is a crucial downstream signal of both RAS and RET pathways, and is aberrantly activated in NF1-deficient malignant peripheral nerve sheath tumours, phaeochromocytomas and paragangliomas." (PMID 29166454, 2017).
pheochromocytoma (continued). "Accumulating evidence indicates that CLA occurred in 42.3% (33/78) of 78 RET mutation carriers in 14 MEN 2/CLA families, similar to the approximately 50% morbidity for pheochromocytoma in MEN 2A." (PMID 26356818, 2015). "Somatic mutations in sporadic pheochromocytoma/paraganglioma has been identified in VHL, RET, SDHB, and SDHD but their frequency was reported to be low." (PMID 26347711, 2015). "In 2006, a study comprising a larger number of patients with pheochromocytoma/paraganglioma showed that 33% of the patients carried germline mutations in one of the following genes: VHL, RET, NF1, SDHB, and SDHD." (PMID 24899893, 2014). "Childhood pheochromocytoma is rare in MEN 2, but reports at 12 years of age have occurred for both the 918 and 634 RET mutations." (PMID 24899893, 2014). "In this manuscript, we report a rare case of a patient who was affected by bilateral pheochromocytomas as the first manifestation of MEN2A, whose subsequent screening for RET mutation identified S891A." (PMID 24449023, 2014). "Quantities of susceptibility genes mutation, including RET, SDHB, and NF-1, have been recognized as being possible to the development of AMH to pheochromocytoma." (PMID 25246937, 2014). "Second, genetic analysis for apparently sporadic phaeochromocytoma should include sequencing of exon 8 on the RET gene as we have seen that this can be the earliest clinical manifestation of MEN2A with this genotype." (PMID 24616773, 2013). "Activating mutations in RET have been documented in human PTC and MTC, multiple endocrine neoplasia 2 syndromes, pheochromocytoma, and paragangliomas that are known to drive tumor cell growth." (PMID 22630170, 2012). "Discovery of a known MEN2 pathogenic RET mutation within a family leads to screening for MTC, pheochromocytomas, or parathyroid hyperplasia, and potentially prophylactic thyroidectomy to increase survival rate for the intractable, aggressive MTC." (PMID 22545224, 2012). "To evaluate the link between hypoxia and Warburg effect, we studied mitochondrial electron transport, angiogenesis and glycolysis in pheochromocytomas induced by germ-line mutations in VHL, RET, NF1 and SDH genes." (PMID 19763184, 2009). "Somatic RET mutations have been found in only 23-40% of sporadic MTC and 10% of sporadic phaeochromocytomas." (PMID 8695346, 1996). "One patient with RET mutation has an active metastatic disease (MTC and pheochromocytoma), being under treatment with tyrosine kinase inhibitors; other two patients with RET mutation developed recurrent MTC but no recurrence of PHEO." (PMID 38318817, 2024). "RET rearrangements have been identified in sporadic cases of pheochromocytoma, without MEN 2 syndrome association." (PMID 37627175, 2023). "The first RET pathogenic variants were reported in 1993 by two independent groups, and since then, more than 100 pathogenic RET variants have also been identified in a large percentage of MEN2A patients who were clinically diagnosed with MTC, pheochromocytoma, or both." (PMID 37374115, 2023). "18F-FDG is also less precise in RET-related pheochromocytomas." (PMID 35205664, 2022). "The major mutations associated with pheochromocytoma are von Hippel-Lindau gene (VHL), REarranged during Transfection (RET) proto-oncogene, neurofibromatosis type 1 gene (NF1), genes encoding four succinate dehydrogenase complex subunits (SDHx; i.e., SDHA, SDHB, SDHC, and SDHD genes)." (PMID 35932074, 2022). "detected RET fusion products in pheochromocytomas and MTC samples." (PMID 35957881, 2022). "MEN2A, the predominant phenotype of MEN2, is caused by germline mutations in the RET proto-oncogene that predispose carriers to an increased risk to development of medullary thyroid cancer (MTC), pheochromocytoma, and primary hyperparathyroidism to different degrees." (PMID 35846296, 2022).
pheochromocytoma (continued). "Pheochromocytoma susceptibility may be associated with germline mutations in the tumor-suppressor genes VHL and NF1 and in the proto-oncogene RET, and recently has been associated with germline SDHD mutations." (PMID 32244473, 2020). "In addition, the rate constant for baseline catecholamine secretion was found to be 20-fold higher in VHL- than in RET-related pheochromocytoma." (PMID 31390824, 2019). "For example, data derived from microarrays and proteomics have shown reduced expression of various components of the regulated secretory pathway (e.g., SNAP25, syntaxin, rabphilin 3A, annexin) in VHL-related pheochromocytomas compared to RET-related pheochromocytomas." (PMID 31390824, 2019). "Besides RET and HRAS, FGFR1 is only the third protooncogene found to be recurrently mutated in pheochromocytomas." (PMID 29159601, 2018). "Previous reports in humans, based on gene expression profiling and unsupervised hierarchical clustering, demonstrate a tight association between pheochromocytomas with VHL and SDH mutations, which distinguishes them from pheochromocytomas with MEN2, RET, and NF1 mutations." (PMID 24465590, 2014). "In sporadic pheochromocytomas, somatic mutations of VHL or RET are found in less than 10% of tumors, suggesting a possible role in tumorigenesis, whereas the prevalence and role of such mutations in hereditary pheochromocytomas such as those occurring in MEN 2 is not known." (PMID 16707008, 2006). "Thus, VHL and RET appear to have only a minor role in the pathogenesis of sporadic phaeochromocytoma." (PMID 15505628, 2004). "Family screening was negative for RET mutations in her mother and brother; her father, who died at 37 from uncontrolled hypertension, may have had an undiagnosed pheochromocytoma." (PMID 41918669, 2026). "Whether RET associated PPGLs are more likely to declare during pregnancy needs further study; certainly, several case reports attest to the often-dramatic presentation of MEN2-related pheochromocytoma in pregnancy." (PMID 36637675, 2023). "Patients with germline RET variants are encouraged to avoid dopamine D2 agonists and beta-adrenergic antagonists until pheochromocytoma is sufficiently ruled out, as these agents may trigger adverse events." (PMID 35685436, 2022). "Moreover, recent studies indicate that up to 25% of pheochromocytoma patients have a genetic background (NF1, VHL, SDHD, SDHB or RET gene mutations) and thus both the patients and their closest blood relatives require wide multidisciplinary diagnostics as well as long-term follow-up." (PMID 31137898, 2019). "Coincidentally, germline RET mutations are associated with multicentric or bilateral tumors and secondary benign endocrine conditions; 50% of both MEN2A and MEN2B cases presented with pheochromocytoma." (PMID 40731793, 2025). "The RET genetic analysis is essential and obligatory in MEN2A cases and in all cases with clinical diagnosis of MTC or pheochromocytoma." (PMID 35846296, 2022). "RNA expression levels of RET gene with other pheochromocytoma-related genes and UPR markers, Bip/GRP78, CHOP, ATF4, and ATF6, in her pheochromocytoma relative to her normal adrenal gland were analyzed by real time PCR (RT-PCR)." (PMID 32571297, 2020). "We demonstrate extreme increases in RET mRNA expression and UPR markers in her pheochromocytoma compared to those in her normal adrenal gland." (PMID 32571297, 2020). "These regions have also been shown to be affected in RET, NF1 and sporadic paragangliomas/pheochromocytomas, indicating the potential presence of driver genes on these autosomes." (PMID 28099933, 2017). "Transcription analysis showed these tumors to be similar to RET- and NF1-mutant pheochromocytomas and paragangliomas." (PMID 28187001, 2017).